PRL (prolactin)
Diseases named in the same sentence as PRL in open-access papers (continued):
Sharing a sentence is not in itself a finding about the gene and the disease.
prostate tumors (5 papers, 2012 to 2021). "The amplification of castrate-resistant, stem/progenitor cells in Pb-PRL prostates further supports a role for PRL signaling in the progression of prostate tumors including escape to androgen deprivation." (PMID 31269779, 2019). "Together, these findings highlight an important role of PRL/STAT5 in the development of prostate tumors." (PMID 31269779, 2019). "PRL is also involved in prostate tumor growth, acting as a survival factor for epithelial cells, and PRL expression was correlated with tumor differentiation degree." (PMID 23317095, 2013). "In addition, the increase in circulating levels of prolactin is related to the pathogenesis of prostatic tumours (reviewed in Costello and Franklin)." (PMID 34158080, 2021). "Indeed, PRL is expressed in more than half of prostate tumors (including local, locally advanced, and hormone refractory) and over 60% metastases, and its level of expression in primary tumors is positively associated with high Gleason score (i.e., high disease severity)." (PMID 31269779, 2019).
psychological distress (5 papers, 2022 to 2026). "This reduction in maternal stress is crucial, as psychological distress can elevate cortisol levels, which antagonizes the milk-ejection reflex and may suppress prolactin secretion." (PMID 41244798, 2025). "Consistent with a previous study, the present study indicated that psychological distress could predicate the occurrence of TEF, the reason was that distress is thought relevant to sexual disorders or elevated prolactin levels." (PMID 36687954, 2022). "Long-term high psychological distress levels tend to produce more negative emotions, which may reduce men’s sexual desire by stimulating the secretion of prolactin." (PMID 36687954, 2022).
sellar tumors (5 papers, 2013 to 2025). "The sellar tumor corresponded to a PA showing positive immunohistochemistry for prolactin and follicle-stimulating hormone (FSH)." (PMID 35165602, 2022). "Serum prolactin concentration was elevated in most cases, probably due to pituitary stalk compression by the sellar tumor, the so-called stalk effect." (PMID 24119690, 2013).
sleep disorder (5 papers, 2021 to 2025). A change from the patient's baseline sleeping pattern, in the hours slept and/or an alteration/dysfunction in the stages of sleep. "With this observational, retrospective study, we found that, in a selected sample of patients admitted to hospital with neurologic/psychiatric and sleep disorders, increased levels of PRL is a relatively frequent finding when tested (55 out 130, 42.3%)." (PMID 34942875, 2021). "However, due to limitations in the target population and study design, the relationship between prolactin levels in prolactinoma patients and sleep disorders is still controversial." (PMID 38572480, 2024). "We were able to identify, among subjects with increased levels of PRL, a subgroup of patients in whom no other medical, neurologic, psychiatric, or sleep disorder (or drug) potentially causing EDS was present, but not among those with normal PRL." (PMID 34942875, 2021). "Furthermore sleep disorders can influence the levels of PRL which, in such a case, seem to be a secondary expression of a sleep disturbance and might not translate directly into an increased daytime sleepiness." (PMID 34942875, 2021). "Among subjects with increased PRL, eight had no other neurologic/psychiatric or sleep disorder (or drug) potentially causing EDS; these participants, at polysomnography, had time in bed, sleep period time, and total sleep time longer than those with EDS associated to another condition." (PMID 34942875, 2021). "Sleep disorders may also affect reproductive hormones such as thyroid-stimulating hormone (TSH), follicle-stimulating hormone (FSH), and prolactin (PRL)." (PMID 39950025, 2025). "The GEE model showed that the group without sleep disorders and the group with sleep disorders had significantly different PRL levels at each time point (P < 0.05)." (PMID 38572480, 2024). "Patients without sleep disorders had lower PRL levels than those with sleep disorders (P = 0.003)." (PMID 38572480, 2024). "In fact, sleep disorders such as obstructive sleep apnea, when treated with continuous positive airway pressure therapy, resulted in a decrease in prolactin levels and improvement in fertility, demonstrating the reversibility of the negative effects of sleep disorders on fertility." (PMID 33924000, 2021).
somnolence (5 papers, 2020 to 2025). "Common TEAEs reported in the aripiprazole group were somnolence, lethargy, decrease in blood prolactin, influenza-like illness, tremor, and akathisia." (PMID 39026306, 2024). "Some of the reported comorbidities (somnolence, extrapyramidal disorder, prolactin increase) are typical side effects of antipsychotic drugs, and may in fact have eventually arisen from the previous medication of the patients." (PMID 36918846, 2023).
steatosis (5 papers, 2020 to 2025). Increased lipid within the cytoplasm of cells. "In human studies, lower prolactin levels were found in patients with more severe hepatic steatosis, suggesting a possible involvement of prolactin in the progression of this disease." (PMID 35448486, 2022). "They believed that there is a new link between the central nervous system and the liver, and PRL improves steatosis of the liver through PRLR and fat/CD36." (PMID 32477263, 2020). "PRL levels at the 3 time points were inversely associated with the absolute value of SJL (r = −0.36, −0.32, −0.47, respectively; P < 0.05) and the histopathological degree of steatosis (r = −0.29, −0.34, −0.31, respectively; P < 0.05)." (PMID 40462123, 2025).
systemic sclerosis (5 papers, 2015 to 2025). A chronic disorder, possibly autoimmune, marked by excessive production of collagen which results in hardening and thickening of body tissues. "Elevated PRL levels have been documented in a range of 13%–59% of patients diagnosed with systemic sclerosis, suggesting a potential hormonal involvement or endocrine dysregulation in this complex autoimmune connective tissue disorder." (PMID 41476991, 2025). "High levels of PRL have been reported in 13–59% of patients with systemic sclerosis." (PMID 29483903, 2018).
Tremor (5 papers, 2022 to 2025). An unintentional, oscillating to-and-fro muscle movement about a joint axis. "The incidence of the EPS-related TEAEs of tremor and akathisia were 10.9% (5/46) vs. 20.0% (3/15) and 8.7% (4/46) vs. 20.0% (3/15), respectively, and the incidence of decreased prolactin was 19.6% (9/46) vs. 0% (0/15)." (PMID 39026306, 2024). "Mild tremor, insomnia, and weight gain were observed as side effects in some cases, but none were severe, and no clinically significant changes in serum prolactin levels or other findings were detected." (PMID 41011153, 2025).
vitiligo (5 papers, 2018 to 2024). Generalized well circumscribed patches of leukoderma that are generally distributed over symmetric body locations and is due to autoimmune destruction of melanocytes. "Although not considered a classical sexual hormone, prolactin has received much attention from researchers to uncover a sex-linked etiology of vitiligo." (PMID 39735711, 2024). "With regard to for the studies on patients with vitiligo, contradictory results have been published so far about the presence of significantly increased serum prolactin levels compared to healthy subjects: some authors have found increased levels, whereas others do not." (PMID 39735711, 2024). "However, it is worth mentioning that PRL is also able to modulate stress response and regulate emotions so that, from this point of view, prolactin could influence vitiligo at the psychological level." (PMID 39735711, 2024). "Serum levels of fT3, fT4, TSH, estradiol, testosterone, prolactin, cortisol, and ACTH in vitiligo patients compared with control subjects." (PMID 29922226, 2018). "The positive correlation observed between tissue prolactin and PRLR levels in vitiligo patients, supported the hypothesis of an autocrine/paracrine activity of prolactin able to modify the melanocyte microenvironment." (PMID 39735711, 2024). "The study found a negative correlation between the duration of vitiligo and AMH, prolactin, and ovarian volume, indicating that longer exposure to the disease may be associated with reduced ovarian reserve." (PMID 39717103, 2024).
Abdominal obesity (4 papers, 2021 to 2024). Excessive fat around the stomach and abdomen. "Furthermore, MetS development is highly affected by endocrine hormones such as prolactin (PRL) hormone which affect IR and central obesity." (PMID 39663784, 2024). "To-tal FSFI was positively associated with prolactin level but negatively associated with central obesity in the non-PCOSgroup; it was negatively correlated with marital duration in the PCOS group." (PMID 33497050, 2021).
allergies (4 papers, 2021 to 2024). "In allergies, such as eosinophilic esophagitis, PRL has been studied from the point of view of the T cells involved in inflammation: CD3+, CD4+, and CD8+, which are of great importance because they produce cytokines of the Th2 profile, PRL can regulate the production of these cytokines." (PMID 39840271, 2024).
alopecia areata (4 papers, 2013 to 2024). Loss of scalp and body hair involving microscopically inflammatory patchy areas. "As comorbidities, patient has persistent increased levels of prolactin, gastroesophageal reflux disease with hiatal hernia and alopecia areata." (PMID 31822863, 2020). "Whether PRL and PRLR signalling play a significant role in the aetiopathogenesis of alopecia areata, potentially related to psychological stress, and to what extent this is due to systemic versus intracutaneous PRL production remain to be clarified." (PMID 39000207, 2024). "Studies examining the role of PRL in alopecia areata are limited." (PMID 39000207, 2024). "Given that substance P is a key mediator of neurogenic skin inflammation, and may partially explain the effects of psychological stress on hair growth in alopecia areata and telogen effluvium, it is interesting to note that substance P decreased PRL IR." (PMID 23626671, 2013).
Arrhythmia (4 papers, 2019 to 2025). Any cardiac rhythm other than the normal sinus rhythm. "Domperidone was previously approved by FDA but was recently removed from the market in the US because of its potential harmful effect on children when it is used for increasing lactation by increasing prolactin levels and its association with risk of cardiac arrhythmia in older patients." (PMID 31059522, 2019). "Another study confirmed that PRL prolongs cardiac repolarization at the cellular level in LQT2 syndrome, affecting ion channels and calcium and ryanodine receptors, which may contribute to an increased risk of arrhythmia." (PMID 41244055, 2025).
asthenozoospermia (4 papers, 2017 to 2022). "A positive correlation was found between age and FSH, PRL and LH in the asthenozoospermia group (p=0.06; r=0.609, p=0.012; r=0.564, respectively)." (PMID 29492471, 2017).
celiac disease (4 papers, 2005 to 2025). An autoimmune genetic disorder with an unknown pattern of inheritance that primarily affects the digestive tract. "Thus, the high biopsy morning prolactin levels in depressed adolescents with untreated coeliac disease in the present study could be associated with serotonergic dysfunction." (PMID 15774013, 2005). "Compared to children with celiac disease following a gluten‐free diet, those who continue to consume gluten demonstrate markedly elevated PRL levels." (PMID 41476991, 2025). "We studied the possible effects of a gluten-free diet on psychiatric symptoms, on hormonal status (prolactin, thyroidal function) and on large neutral amino acid serum concentrations in adolescents with coeliac disease commencing a gluten-free diet." (PMID 15774013, 2005). "Elevated serum PRL levels observed in untreated celiac disease patients may potentially indicate a primary immunological mechanism that triggers intestinal mucosal damage and subsequent clinical manifestations." (PMID 41476991, 2025). "They suggest that prolactin may play a part in the immune modulation of the intestine and could thus serve as a potential marker for coeliac disease activity." (PMID 15774013, 2005). "A significant decrease in psychiatric symptoms was found at 3 months on a gluten-free diet compared to patients' baseline condition, coinciding with significantly decreased coeliac disease activity and prolactin levels and with a significant increase in serum concentrations of CAAs." (PMID 15774013, 2005). "On the other hand, in the present study also non-depressed adolescents with coeliac disease had higher than normal biopsy morning prolactin levels." (PMID 15774013, 2005).
cocaine addiction (4 papers, 2019 to 2023). "The KEGG pathway enrichment analysis showed that six pathways were significantly enriched, containing amphetamine addiction, cocaine addiction, dopaminergic synapse, cholinergic synapse, prolactin signaling pathway, and nicotine addiction." (PMID 31579613, 2019).
dementia (4 papers, 2022 to 2025). Loss of intellectual abilities interfering with an individual's social and occupational functions. "Our findings implicate hippocampal DNMT as a therapeutic target for PrL DBS and pave way for the potential use of non-invasive neuromodulation modalities against dementia." (PMID 36818556, 2023).
dysplasia (4 papers, 2019 to 2023). A usually neoplastic transformation of the cell, associated with altered architectural tissue patterns. "A 44-months old female laboratory New Zealand white rabbit with a prolactinoma and elevated serum prolactin was diagnosed with mammary hyperplasia, dysplasia and cystic mammary adenocarcinoma associated with secretory activity." (PMID 31581718, 2019). "Long-term antipsychotic drug treatment may be the main cause for SDs in psychotic patients, through a plethora of different mechanisms, including prolactin dyscrasia, histamine-mediated sedation, and serotonin-induced sexual demotivation." (PMID 34777053, 2021). "Indeed, a major cause of impairment may be the patients' long-term drug treatment, which affects sexuality through a plethora of different mechanisms, including prolactin dyscrasia, histamine-mediated sedation, and serotonin-induced sexual demotivation." (PMID 34777053, 2021).
leishmaniasis (4 papers, 2023 to 2025). Infectious disease that is transmitted through the bite of hematophagous female phlebotomine sand flies. "In KEGG pathway, the candidate target genes were significantly enriched in prolactin signaling pathway, tuberculosis, leishmaniasis, pathways in cancer and Kaposi sarcoma-associated herpesvirus infection." (PMID 37717047, 2023). "According to KEGG analysis, the hub genes were involved in various signalling pathways, including the prolactin signalling pathway, leishmaniasis, the IL-17 signalling pathway, growth hormone synthesis, secretion and action." (PMID 36765335, 2023). "Thus, the role of prolactin in leishmaniasis immunity especially over various disease presentations and parasite species requires further investigation." (PMID 39781597, 2025).
leukemia (4 papers, 2015 to 2023). A malignant (clonal) hematologic disorder, involving hematopoietic stem cells and characterized by the presence of primitive or atypical myeloid or lymphoid cells in the bone marrow and the blood. "Disruption of the PRLR signaling, either using a mutant PRL or a dominant-negative isoform of PRLR, reduced the leukemia burden in vivo, in xenotransplantation assays." (PMID 37208719, 2023). "Interestingly, the migration capacity to peripheral organs of both PRL mut- and PRLR short-expressing AML cells was severely diminished, as observed in the leukemia levels in spleen." (PMID 37208719, 2023). "Other studies using permeabilized cells derived from growth hormone and prolactin-secreting pituitary GH3 cells, human promyelocytic leukemia cells, human neutrophils, mast cells, and regulatory T cells have demonstrated that vesicle formation from the TGN during exocytosis was dependent on PLD." (PMID 26492088, 2015). "ENCODE annotation data identified the CpG correlated to expression of PRL to be located in a heterochromatin block in the GM12878 B-lymphocyte cell line, although within an active promoter and weak enhancer in human embryonic stem cell line (H1-hESC) and leukaemia cell line (K562), respectively." (PMID 26798410, 2016).
lipid metabolism disorder (4 papers, 2020 to 2024). "In conclusion, our research shows that the pathophysiology of GLM and PCM is related to multiple immune variables, including immune cells, connecting cytokines, prolactin, hypersensitivity reactions driven by milk stasis, lipid metabolic disorders, and immune inflammation associated pathways." (PMID 39148739, 2024). "Therefore, it is necessary to further study whether there are other mechanisms related to hepatic microcirculatory dysfunction caused by lipid metabolism disorder under low PRL condition." (PMID 32477263, 2020). "In addition, other immune-related factors (prolactin, hypersensitivity reactions due to milk stasis, lipid metabolism disorders, and immune-inflammation-related pathways) also play an important role in the pathogenesis of GLM and PCM." (PMID 39148739, 2024). "Furthermore, NCNL can significantly improve the glucose and lipid metabolism disorders and affect amino acid metabolism through PI3K-Akt, insulin resistance, and prolactin pathways to achieve its therapeutic effect." (PMID 34221092, 2021).
malnutrition (4 papers, 2021 to 2026). Inadequate nutrition resulting from poor diet, malabsorption, or abnormal nutrient distribution. "Reduced triiodothyronine and prolactin values are associated with arterial stiffness, while also being markers of malnutrition." (PMID 37510208, 2023). "Thymus growth and function is regulated by several hormones including Leptin, Prolactin and Growth hormone, mediated by insulin-like growth factor 1, all of which are low in malnutrition." (PMID 33397296, 2021). "Several factors could contribute to the impairment of reproductive function, including malnutrition, an increase in stress hormones such as prolactin, or the secretion of cytokines by cancer tissue." (PMID 37370751, 2023). "Therefore, we speculate that if we detect and treat the inflammatory syndrome, respectively the malnutrition, the triiodothyronine, and prolactin levels, probably the value of PWV can be influenced." (PMID 37510208, 2023).
measles (4 papers, 2021 to 2025). A highly contagious viral infection caused by the measles virus. "Some hormone receptors are used by viruses to facilitate cell entry, and although this has not been shown for GH, prolactin, or their receptors, it is notable that the protein nectin-4, which interacts with the prolactin receptor, is used in this way by some viruses, including measles." (PMID 40105703, 2025).
memory impairment (4 papers, 2013 to 2025). "Late toxicities of grade 1 or 2 were observed in 19 patients: 9 with hearing loss, 5 with xerostomia, 1 with dysphagia, another with reduced prolactin, and 3 with unilateral white matter changes in the temporal lobe (1 also experienced memory loss)." (PMID 31752953, 2019).
myeloma (4 papers, 1983 to 2023). "Although PRL has been shown to be proapoptotic in other tissues or cell types (e.g. keratinocytes, chondrocyte, human myeloma-derived cell lines), the apoptotic signaling mechanism has not been described so far for PRLR." (PMID 24859278, 2014).